HSD17B3 (hydroxysteroid 17-beta dehydrogenase 3)
Description:
Catalyzes the conversion of 17-oxosteroids to 17beta-hydroxysteroids. Favors the reduction of androstenedione to testosterone. Testosterone is the key androgen driving male development and function. Uses NADPH while the two other EDH17B enzymes use NADH. Androgens such as epiandrosterone, dehydroepiandrosterone, androsterone and androstanedione are accepted as substrates and reduced at C-17. Can reduce 11-ketoandrostenedione as well as 11beta-hydroxyandrostenedione at C-17 to the respective testosterone forms.
Synonyms: EDH17B3; SDR12C2
Tractability: Small molecule: a high-quality ligand is known; it belongs to a druggable protein family. PROTAC: a small molecule that binds it is known.
Target class: Enzyme; Oxidoreductase
Gene: Protein-coding gene on chromosome 9 (96,235,306 to 96,302,176, reverse strand). Ensembl gene ENSG00000130948.
Subcellular location: Endoplasmic reticulum
Subcellular location (Human Protein Atlas): Vesicles
Pathways (Reactome):
Metabolism: Androgen biosynthesis; Synthesis of very long-chain fatty acyl-CoAs
Gene Ontology:
Molecular function: protein binding; testosterone dehydrogenase (NADP+) activity; 17-beta-hydroxysteroid dehydrogenase (NADP+) activity; estradiol 17-beta-dehydrogenase [NAD(P)+] activity; oxidoreductase activity, acting on CH-OH group of donors
Biological process: androgen biosynthetic process; male genitalia development; steroid biosynthetic process; lipid biosynthetic process; testosterone biosynthetic process
Cellular component: endoplasmic reticulum; endoplasmic reticulum membrane; intracellular membrane-bounded organelle
Genetic constraint (gnomAD): Loss-of-function variants: 25 observed, 38.65 expected, observed/expected ratio (o/e) 0.65, 90% interval 0.47 to 0.9. The upper end of that interval is the gene's LOEUF score, 0.9, which puts it in group 3 of 6, group 1 being the genes least tolerant of losing a copy. Missense variants: 297 observed, 369.49 expected, observed/expected ratio (o/e) 0.8, 90% interval 0.73 to 0.88. Synonymous variants: 123 observed, 145.97 expected, observed/expected ratio (o/e) 0.84, 90% interval 0.73 to 0.98.
Homologues: Orthologues: chimpanzee HSD17B3 (99% identical), macaque HSD17B3 (95% identical), pig HSD17B3 (80% identical), rabbit HSD17B3 (80% identical), rat Hsd17b3 (74% identical), mouse Hsd17b3 (72% identical), guinea pig HSD17B3 (69% identical), tropical clawed frog hsd17b3 (54% identical), zebrafish hsd17b3 (33% identical). Paralogues in human: HSD17B12 (40% identical), HSDL1 (33% identical), HSD17B6 (22% identical), RDH16 (21% identical), HSD17B11 (20% identical), HSD17B13 (20% identical), RDH10 (20% identical), DHRS3 (19% identical), DHRS9 (19% identical), RDH5 (19% identical), SDR16C5 (19% identical), SDR9C7 (18% identical), and 13 more.
Diseases named in the same sentence as HSD17B3 in open-access papers:
HSD17B3 is named in the same sentence as 36 diseases in open-access papers, as found by Europe PMC text mining. Sharing a sentence is not in itself a finding about the gene and the disease. The quoted sentences say what the papers report.
hypospadias (9 papers, 2018 to 2025). Hypospadias is the displacement of the urethral meatus on the ventrum of the penis. "Any mutation in the encoding gene (HSD17B3) can lead to varying degrees of undervirilization of the affected male, ranging from completely undervirilized external female genitalia to predominantly male with micropenis and hypospadias." (PMID 28739554, 2018). "Moreover, three studies found that key enzymes involved in testosterone synthesis, represented by Cyp11a1, Cyp17a1, Hsd3b, Scarb1, Star, Hsd17b3 and Srd5α2, were significantly reduced at the genetic level in DBP- or DEHP-induced hypospadias male fetal rats." (PMID 39698037, 2024). "Polymorphisms, mutations, and epigenetic changes in the AR, CYR61, HSD17B3, HSD3B1, MAMLD1, SRD5A2, and STARD3 have been associated to hypospadias risk in severe types of hypospadias that have not been found in mild hypospadias." (PMID 33425810, 2020).
prostate carcinoma (7 papers, 2015 to 2022). A carcinoma that arises from epithelial cells of the prostate gland. "Inhibition of HSD17B3 would block testosterone synthesis in testis which would be beneficial in case of desired testosterone deprivation, e.g., in prostate cancer treatment." (PMID 35208174, 2022). "We identified the β-hydroxysteroid-dehydrogenases HSD17B1 and HSD17B3 to be significantly up-regulated in metastatic compared to non-metastatic prostate cancer; they also correlated with the intensity of SR-BI expression." (PMID 26251134, 2015).
endometriosis (3 papers, 2012 to 2025). The growth of functional endometrial tissue in anatomic sites outside the uterine body. "Although Ser/Gly of residue 289 of HSD17B3 was proposed to be a neutral polymorphism, we found that the phosphorylation of 289Ser in HSD17B3 may decrease the risk of endometriosis." (PMID 23139742, 2012). "Furthermore, conversion of 289Gly to 289Ser (G to A of rs2066479) of HSD17B3 is associated with a decreased risk of endometriosis in younger women." (PMID 23139742, 2012). "Collectively, the GG homozygous genotype of polymorphism of HSD17B3 (289Gly/Gly) (wild type) may play a crucial role in the development of endometriosis in the presence of AA homozygous genotype of polymorphism of FSHR (680Asn/Asn) (wild type)." (PMID 23139742, 2012). "In this setting, both heterozygous mutant SNP (genotype AG, 289Ser/Gly) and homozygous mutant SNP (genotype AA, 289Ser/Ser) of HSD17B3 showed a significantly decreased risk of endometriosis (P = 0.005; OR = 0.57) and P = 0.02; OR = 0.69), respectively, as compared to the controls (n = 337)." (PMID 23139742, 2012). "In contrast, in endometriosis patients younger than 37 years (n = 176), combined homozygous and heterozygous mutant SNP (genotype AA+AG, 289Ser/Ser+289Ser/Gly) of HSD17B3 showed a significantly lower risk of endometriosis (P = 0.007; OR = 0.59) in comparison with the controls (n = 337)." (PMID 23139742, 2012). "Similarly, the upregulation of HSD17B3 expression may increase the risk of endometriosis." (PMID 40313549, 2025). "We also identified an association between mutant genotypes in FSHR, HSD17B3 and CYP19 and decreased risks of endometriosis." (PMID 23139742, 2012). "Results of this study suggest that non-synonymous polymorphisms of FSHR, HSD17B3 and CYP19 genes may modulate the risk of endometriosis in Taiwanese Chinese women." (PMID 23139742, 2012). "Statistically significant differences were observed in the expression levels of six hub genes (ACSL4, CYP2C18, CYP2C9, HSD17B3, HSDL2, and PTGS2) between the Endometriosis and Control groups of the combined GEO datasets (p < 0.001)." (PMID 40313549, 2025). "Because these 4 nsSNPs reside in 3 genes related to estrogen synthesis (HSD17B3, FSHR and CYP19), endogenous production of more estrogens, instead of slowing the degradation of estrogens and their metabolites, may be more strongly associated with the risk of endometriosis." (PMID 23139742, 2012). "Our results did not identify endometriosis-specific amino acid changes in HSD17B1 but detected endometriosis preferential structural changes of HSD17B3, CYP19, and FSHR." (PMID 23139742, 2012).
androgen insensitivity syndrome (2 papers, 2019 to 2024). Androgen insensitivity syndrome (AIS) is a disorder of sex development (DSD) characterized by the presence of female external genitalia, ambiguous genitalia or variable defects in virilization in a 46,XY individual with absent or partial responsiveness to age-appropriate levels of androgens. "HSD17B3 was also found to be highly expressed in adult Sertoli cells in a patient with complete androgen insensitivity syndrome (CAIS), which could be due to a lack of HSD17B3 shift from Sertoli to Leydig cells and could point to a role of androgen signaling in that process." (PMID 39139451, 2024).
Diabetes (2 papers, 2018 to 2025). "A pharmacogenetic analysis using a genome‐wide approach in the ACCORD (Action to Control Cardiovascular Risk in Diabetes) trial identified HSD17B3, SMAD3, and IPO11 as genetic markers of fenofibrate response." (PMID 30371334, 2018). "As reported in prior studies, STZ-induced diabetes decreased Star expression, consistent with our findings, whereas Cyp11a1 and Hsd17b3 mRNA levels showed no significant changes." (PMID 41158715, 2025).
Disorder of Sex Development (2 papers, 2022 to 2024). "Homozygous or compound heterozygous HSD17B3 mutations block the synthesis of testosterone in the fetal testis, resulting in a Disorder of Sex Development (DSD)." (PMID 36077423, 2022).
Hydrocephalus (2 papers, 2024 to 2025). Hydrocephalus is an active distension of the ventricular system of the brain resulting from inadequate passage of CSF from its point of production within the cerebral ventricles to its point of absorption into the systemic circulation. "However, none of the three neighboring genes (Hsd17b3, Slc35d2, Zfp367) within 100 kb of BAC/APOL1-G1 insertion site (mm39, chr13: 64,197,419) were plausibly related to hydrocephalus." (PMID 39803526, 2024).
Infertility (2 papers, 2022 to 2024). "HSD17B3 deficiency causes male pseudohermaphroditism, leading to ambiguous or female external genitalia, cryptorchidism, and infertility." (PMID 39139451, 2024). "While HSD17B3 doesn’t seem to be crucial for basal testosterone production in mice, HSD17B3 deficiency in humans causes abnormal masculinization, infertility, and very high rates of gender dysphoria, which confirms its role in the development of major sexual characteristics." (PMID 39139451, 2024).
Primary amenorrhea (2 papers, 2021 to 2022). "The diagnosis of HSD17B3 deficiency should be considered in patients with primary amenorrhea and a mild degree of virilization." (PMID 34768925, 2021). "Mutations in the HSD17B3 gene cause 46,XY disorders of sex development (46,XY DSD), pathologies often difficult to identify and which are often confirmed only at older ages, when an affected XY female presents with primary amenorrhea or develops progressive virilization." (PMID 36675662, 2022).
17-alpha hydroxylase deficiency (1 paper, 2025). "Two patients had variants in HSD17B3 and CYP17A1 genes, resulting in 17-beta hydroxysteroid dehydrogenase III (17βHSD-3) deficiency and 17-alpha hydroxylase deficiency (17OHD), respectively." (PMID 39936125, 2025).
acne (1 paper, 2021). An inflammatory process of the sebaceous glands which is characterized by comedones, nodules, papules and/or pustules on the skin. "A Chinese study found that HSD3B1 (Hydroxy-Delta-5-Steroid Dehydrogenase, 3 Beta- and Steroid Delta-Isomerase 1) rs6428829 and AAT haplotype, and HSD17B3 (Hydroxysteroid 17-Beta Dehydrogenase 3) H8 haplotype were significantly associated with acne risk." (PMID 33849530, 2021).
Adrenal insufficiency (1 paper, 2025). Insufficient production of steroid hormones (primarily cortisol) by the adrenal glands. "Mutations in genes related to steroid biosynthesis (such as CYP11A1, CYP17A1, HSD3B2, HSD17B3, and StAR) will lead to androgen synthesis disorders with adrenal insufficiency besides the SRD5A2 gene mutation which results in the insufficient transformation of dihydrotestosterone from testosterone." (PMID 40247401, 2025).
disorder of sexual differentiation (1 paper, 2024). A congenital disorder characterized by abnormalities in the development of the sexual characteristics. "Interestingly, a few patients with Disorders of Sexual Differentiation (DSD) shared rare pathogenic variants in the SRD5A2, HSD17B3 and HSD3B2 while patients with Glucose and Insulin Homeostasis carried theirs in GCK and HNF1A genes." (PMID 38637882, 2024).
hypogonadism (1 paper, 2024). A disorder characterized by decreased function of the gonads. "Finally, ~10% of men with late‐onset hypogonadism exhibit a phenotype of compensated hypogonadism, with high LH and normal testosterone, similar to steroidogenic compensation in HSD17B3‐deficient adult mice." (PMID 39556387, 2024).
overnutrition (1 paper, 2021). An imbalanced nutritional status resulting from excessive intake of nutrients. "Bull fetuses exposed to maternal overnutrition experienced a decrease in expression of steroidogenic acute regulatory protein (StAR), hydroxysteroid 17-Beta dehydrogenase 3 (HSD17B3), IGF1, IGF2, and IGF1 receptor (IGF1R), genes involved in testes development and steroidogenesis." (PMID 34438674, 2021).
preeclampsia (1 paper, 2024). Preeclampsia is a hypertensive disorder of pregnancy that is characterized by new-onset hypertension with proteinuria presenting after 20 weeks of gestation, and depending on mild or severe forms may initially present with severe headache, visual disturbances, and hyperreflexia. "We identified CYP17A1, HSD17B3, SRD5A1, CYP19A1, CYP11B1, HSD11B1 and HSD11B2 as potentially affected enzymes in preeclampsia." (PMID 39684415, 2024). "mRNA expressions of genes of enzymes with significantly decreased precursor-to-product ratios (i.e., CYP17A1, HSD17B3, CYP11B1 and HSD11B2) was similar in women with preeclampsia and controls, but the RNA levels of these genes were higher in women with preeclampsia." (PMID 39684415, 2024).
type 2 diabetes (1 paper, 2019). "Mutation in HSD17B3 was linked with development of type 2 diabetes, but this variant gene may be responsible for progression of CAD." (PMID 31881747, 2019).
cancer (5 papers, 2010 to 2024). A tumor composed of atypical neoplastic, often pleomorphic cells that invade other tissues. "Since irreparable structural mutations in cells may result in cancer occurrence, we then determined the genetic alterations of SRD5A3, DOLK, SRD5A1, and HSD17B3 in BC." (PMID 34465365, 2021).
tumor (5 papers, 2011 to 2023). "Consistent with this, reanalysis of the TCGA PRAD cohort (n = 497) showed that tumor T-stage progression was associated with SRD5A1 and HSD17B3 gene amplification and gain, but shallow or deep deletion of SHBG and HSD17B2 genes." (PMID 34298692, 2021). "However, it has become better delineated that these tumours also express testis-specific genes such as the luteinising hormone/choriogonadotrophin receptor (LHCGR), insulin-like peptide 3 (INSL3) and 17 β-hydroxysteroid dehydrogenase 3 (HSD17B3)." (PMID 36165736, 2022).
HSD17B3 also shares sentences with these, for which no sentence is quoted: complete androgen insensitivity syndrome (2 papers); seminoma (2); benign prostatic hyperplasia (1); breast carcinoma (1); cryptorchidism (1); glioblastoma (1); hypogonadotropic hypogonadism (1); hypopituitarism (1); Inguinal hernia (1); melanoma (1); Micropenis (1); Obesity (1); Opitz syndrome (1); Parkinson disease (1); persistent müllerian duct syndrome (1); schizophrenia (1); testicular cancer (1).